IFNG (interferon gamma)
Diseases named in the same sentence as IFNG in open-access papers (continued):
Sharing a sentence is not in itself a finding about the gene and the disease.
melanoma (continued). "Melanoma cells treated with either IFNγ or FK866 had a reduction in growth that was further exacerbated upon combination treatment with IFNγ and FK866." (PMID 36900204, 2023). "Further, NAMPT is also known to be secreted from cells and is referred to as extracellular NAMPT (eNAMPT), and the mechanism by which IFNγ alters eNAMPT in melanoma will also be of interest for future studies." (PMID 36900204, 2023). "Ptpn2 knockdown likely increases melanoma cell sensitivity to IFNγ by enhancing STAT1, STAT3, and STAT5 phosphorylation and MHC-I, MHC-II, and PD-L1 expression." (PMID 38022587, 2023). "Melanoma cystine depletion via IFNγ-mediated suppression of glutamate-cystine antiporter system Xc- underlies the immunotherapy-related ferroptosis." (PMID 36003368, 2022). "HLA-DRa also exhibited heterogenous expression in melanoma lesions and cell lines, with IFNγ being a strong inducer of HLA class II expression." (PMID 36389735, 2022). "Collectively, these data show that the strong basal and dynamic induction of IFNγ-R1 expression by STUB1 inactivation results in intensified IFNγ signaling and consequently, IFNγ-dependent sensitization of melanoma cells to cytotoxic T cells in vitro." (PMID 35395848, 2022). "Knocking out EGR4 in T cells triggers an enhanced Ca2+ response and increased IFNγ production in vitro and leads to regulatory T cells loss, Th1 bias, and CTL generation in a mouse melanoma lung colonization model." (PMID 35162934, 2022). "Gene expression profiling in melanoma patients treated with nivolumab (anti-PD1) alone or combined with Ipilimumab (anti-CTLA4) revealed that an IFNγ-driven gene signature was the most predictive feature for clinical responses to these immunotherapies." (PMID 35902886, 2022). "Nonetheless, a role for CD8+ T cells in the retardation of tumor growth in the lungs is plausible as there is a significant induction of TNFα and IFNγ in lung-infiltrating CD8+ T cells in the melanoma-bearing lungs." (PMID 36733396, 2022). "A recent study found that an Fbw7R/+ mutation conferred resistance to PD-1 blockade through impaired dsRNA sensing and IFNγ signaling in a metastatic melanoma and a murine melanoma model." (PMID 35225231, 2022). "Truncating mutations, homozygous deletions, and low protein levels of IFNGR1, IFNGR2, JAK1, JAK2, STAT1, and IRF1 in melanoma patients result in shorter survival than that of patients with wild-type IFNγ signaling genes." (PMID 34385592, 2022). "Knockout of FTO in melanoma cells induces tumor cells to become sensitive to interferon-gamma (IFNγ) in vitro and promotes a sensitizing response of melanoma cells to anti-PD-1 antibody in mice." (PMID 35311150, 2022). "Early on-therapy changes such as upregulation of MHC-I and PD-L1 on melanoma cells and in the microenvironment, were consistent with T-cell activation and local IFNγ release." (PMID 36230753, 2022). "The knockdown of FTO can increase the sensitivity of melanoma cells to interferon gamma and anti‐PD‐1 therapy." (PMID 34647424, 2022). "These elevations in key serum cytokines are consistent with immune stimulation observed in other melanoma models, and together with increased IFNγ gene expression scores, support the use of mavorixafor in combination with checkpoint inhibitor therapies." (PMID 36923305, 2022). "These authors found that manipulating LDHA levels in a mouse model of melanoma results in more infiltrating NK cells and greater expression of IFNγ and granzyme B and greater tumor control in low-LDHA tumors compared to controls." (PMID 35414042, 2022). "As both tested melanoma cell lines offered qualitatively similar behavior in regard to IFNγ treatment and responsiveness towards both ODNs, we focused the following on A375 cells, in which the observed effects were more distinctive." (PMID 36230620, 2022). "This study aims to explore the hypoxic regulation of PD-L1 expression in human melanoma, and its interaction with IFNγ-induced PD-L1 expression." (PMID 34268602, 2022).
melanoma (continued). "IFNγ-stimulated melanoma cells (A375, SK-Mel-28) were treated with different synthetically manufactured oligonucleotides which differed in sequence, length and backbone composition." (PMID 36230620, 2022). "The genes of HAMP, SLC7A5, CYBB, and IFNG were highly expressed in melanoma cell lines, while JDP2, TUBE1, PROM2, GPX2, FBXW7, and ARNTL were lowly expressed in melanoma cell lines." (PMID 35373463, 2022). "In vitro, m6A protein knockdown sensitized melanoma cells to IFNγ to promote to the result of mouse’s anti-PD-1 inhibitors." (PMID 35859893, 2022). "In contrast to NK cells, IVpos and IVneg T cells showed robust expression of IFNγ in the lungs of WT and B2m-/- B16 melanoma-challenged mice compared to control animals." (PMID 36733396, 2022). "In vitro-generated Th17 cells were able to eradicate B16 melanoma in mice, and this effect was reported to be dependent on IFNγ." (PMID 36159781, 2022). "The infiltration of the TME by CD8+ cells and the production of granzyme B and IFNγ have been correlated with decreased metastatic invasion and improved melanoma treatment responses." (PMID 36923305, 2022). "In prior research, histone acetylation mediated by p300/CBP was found to be critical for the transcriptional activation of CTLA-4 licensed by interferon-gamma (IFN-γ) signaling in melanoma cells." (PMID 35585975, 2022). "Some studies have shown that high pre-treatment plasma levels of IFNγ, Interleukin 6 (IL6), and IL10 and Transforming Growth Factor β (TGF-β) are associated with response to anti-PD-1 therapy in melanoma patients." (PMID 35884403, 2022). "A study of melanoma cell lines showed that the induction of IFNγ through depletion of tryptophan contributes to the immune recognition of melanoma cells through an aberrant peptidome." (PMID 36012199, 2022). "We exposed MD55A3 melanoma cells to IFNγ, performed 2D liquid chromatography with mass spectrometry (LC–MS/MS) in duplicate, and searched for W>F in the entire proteome." (PMID 35264796, 2022). "Comparative analysis of the IFNγ-R1High and IFNγ-R1Low melanoma populations revealed that cells carrying sgRNAs targeting IFNGR1 were most abundant in the latter population, again confirming the robustness of the screen." (PMID 35395848, 2022). "A six-gene IFN-γ signature (including IDO1, CXCL10, CXCL9, HLA-DRA, STAT1, and IFNG) was identified in a melanoma cohort of the KEYNOTE-001 study to predict response to pembrolizumab." (PMID 35222540, 2022). "Such hypothesis is supported by the observations that high tumor density of CD8 T cells, high Interferon-γ (IFNγ)-related gene expression signature within the tumor, and high tumor mutational burden all are associated with response to checkpoint inhibitors in melanoma patients." (PMID 35884403, 2022). "IFNγ signaling seems to provide prognostic information in stage III melanoma as shown in a preliminary report of 99 patients." (PMID 35336796, 2022). "Another study using TCR-tg mice and ACT of tumor-specific CD4+ T cells demonstrated that mouse lymphoma and melanoma were rejected through an IFNγ-dependent mechanism that involved indirect activation of CD4+ T cells by secreted antigen expressed on host APCs." (PMID 36159781, 2022). "In melanoma, it has been shown that IFNγ produced by tumor infiltrating T-lymphocytes (TILs) is the main factor inducing expression of PD-L1." (PMID 33809167, 2021). "Here, we found that IL-17 incorporating with IFNγ transforms BMSCs into TA-MSCs to promote tumor growth, which is inhibited by RA treatment in melanoma." (PMID 33889575, 2021). "ML NK cells differentiated from HD and patients with advanced melanoma displayed enhanced IFNγ production and cytotoxicity against melanoma targets." (PMID 34187852, 2021). "ML differentiation of patients' blood NK cells resulted in enhanced ability to produce IFNγ and kill autologous melanoma targets." (PMID 34187852, 2021).
melanoma (continued). "When restimulated with autologous melanoma targets, ML NK cells exhibited a significantly increased IFNγ production compared with control NK cells." (PMID 34187852, 2021). "In another study, NK-derived IFNγ-induced the expression of MHC class I molecules in leukemia cells and decreased their susceptibility to NK cytotoxicity, while in melanoma cells loss of IFNγ signaling components increased tumor cell sensitivity to NKs." (PMID 33801234, 2021). "IFNγ pretreatment potentiated lung colonization of intravenously inoculated B16 melanoma due to upregulation of MHC class I molecules on tumor cells and decreased sensitivity to NK cells." (PMID 33579265, 2021). "Knockdown of FTO made melanoma cells more sensitive to interferon gamma (IFN-γ), thereby reducing the resistance to anti-PD-1 therapy in mice in an adaptive immunity-dependent manner." (PMID 34956201, 2021). "In syngeneic murine models of glioma, melanoma, sarcoma, and colorectal cancer, neoepitope vaccines (delivered with various adjuvants) induced robust antigen-specific IFNγ responses in CD4 and CD8 T cells." (PMID 33033852, 2021). "The B16F0 melanoma cells with BMSCs, which were pretreated with IL-17 and IFNγ jointly, gave more aggressive tumor growth compared to control B16F0 melanoma cells (5.2-fold increase in tumor weight, and 4-fold increase in tumor size)." (PMID 33889575, 2021). "In NSCLC and melanoma, patients with a high level of mRNA expression of IFNG (the gene that encodes IFN-γ) exhibit longer progression-free and overall survival and have higher disease control rates with anti-PD-1 therapies." (PMID 34680282, 2021). "5-, and 1.6-fold increase, respectively) when melanoma mice were co-engrafted with IL-17 and IFNγ transformed TA-MSCs." (PMID 33889575, 2021). "In the immune system, SOCS2 is an IFNγ signature gene in mononuclear phagocytes infiltrating primary human melanoma, and in mouse models acts to limit adaptive anti-tumoral immunity and DC-based priming of T cells." (PMID 34857742, 2021). "For example, inhibiting FTO sensitizes melanoma cells to anti-PD-1 and interferon gamma (IFNγ) treatment." (PMID 34422815, 2021). "Upregulation of IFNγ signature early during therapy correlated with improved outcomes of immune checkpoint blockade in melanoma." (PMID 34201655, 2021). "A tetrad of IL2RA, IL2RG, IFNG, and IL7R genes were determined as hub genes and verified by qRT‐PCR, which were significantly associated with unfavorable prognosis in melanoma." (PMID 34159752, 2021). "ML NK cells from healthy donors (HD) and patients with advanced melanoma were evaluated for their ability to produce IFNγ and kill melanoma targets in vitro and in vivo using a xenograft model." (PMID 34187852, 2021). "Knockdown of FTO sensitized melanoma cells to interferon gamma and sensitized melanoma to anti-PD-1 treatment in mice, depending on adaptive immunity." (PMID 34804948, 2021). "Here, we found that IL-17 cooperating with IFNγ to transform TA-MSCs in supporting tumor growth in melanoma." (PMID 33889575, 2021). "Consistent with previous studies, we observed critically elevated IFNG expression levels present in advanced melanoma were significant correlated with undesired outcomes and reduced immune response in tumor stroma." (PMID 34159752, 2021). "MYO1F mRNA expression was significantly correlated with IFN-γ (i.e., IFNG) in an independent melanoma bulk transcriptomic dataset." (PMID 33619278, 2021). "Another study demonstrated that FTO impeded interferon-gamma (IFN-γ)-induced cytotoxicity in melanoma cells in vitro by upregulating PD-1, CXCR4, and SOX10 through suppression of YTHDF2-mediated RNA decay process." (PMID 33500720, 2021). "In models of syngeneic melanoma and breast cancer, IFNγ commonly overexpressed in the tumoral microenvironment was shown to upregulate PDL1 on tumor associated LECs which consequently inhibited T cell mediated anti-tumor immunity." (PMID 34568423, 2021).
melanoma (continued). "We subcutaneously inoculated B16F0 melanoma cells with normal BMSCs or BMSCs pretreated with IL-17 and IFNγ, respectively, or jointly into C57BL/6 mice." (PMID 33889575, 2021). "Knockdown of FTO sensitizes melanoma cells to interferon gamma (IFNγ) and sensitizes melanoma to anti-PD-1 treatment in mice." (PMID 34526985, 2021). "Our FACS assay showed that the myelocytes, including macrophages, monocytes, and neutrophils, were dramatically increased in peripheral blood when melanoma mice were co-inoculated with IL-17 and IFNγ transformed TA-MSCs (1." (PMID 33889575, 2021). "In the KEYNOTE-012 trial, an 18-gene interferon gamma signature panel that was correlated with IO response in melanoma was studied." (PMID 33916348, 2021). "No significant increase of either myelocytes or T cells was observed in peripheral blood when melanoma mice were co-inoculated with normal BMSCs or BMSCs pretreated with IL-17 or IFNγ individually." (PMID 33889575, 2021). "Overall, our data demonstrated RA treatment significantly blocked IL-17 and IFNγ mediated TA-MSC transformation in promoting tumor growth in melanoma." (PMID 33889575, 2021). "In contrast to ML NK cells from HD, autologous ML NK cells from patients with advanced melanoma also exhibited increased baseline IFNγ production." (PMID 34187852, 2021). "Six stage IIB/C or stage IVM1 a/b melanoma patients were evaluated; all patients generated de novo immune responses against neoepitopes following vaccination, as measured by ex vivo IFNγ ELISPOT of peripheral blood mononuclear cells." (PMID 33033852, 2021). "In murine lungs metastasized by B16F10 melanoma, fully active and highly cytotoxic NK cells produce large amounts of IFNγ." (PMID 33138017, 2020). "Further research into intralesional IFNγ for advanced melanoma was scarce for years, until a small-scale study using a melanoma vaccine (containing class I MHC-restricted melanoma neoantigens) bolstered with IFNγ was completed." (PMID 32455916, 2020). "Yang’s study also demonstrated that knockdown of FTO sensitized melanoma cells to interferon gamma and anti-PD-1 treatments depending on adaptive immunity." (PMID 32299393, 2020). "For this purpose, melanoma cell lines (A375 and A375R) were treated with IFNγ (50 ng/ml) and TNF- α (10 ng/ml)." (PMID 32117720, 2020). "As expected, we observed large quantitative changes in the presentation of protHLAIp when T1185B melanoma cells were treated with IFNγ." (PMID 32157095, 2020). "For example, transcription factors JAK/STAT1, IRF-1 and NFκB are responsible for IFNγ-induced PD-L1 expression in hematopoietic tumors, lung cancer, and melanoma, respectively." (PMID 33193345, 2020). "When cultured in 2D, nearly all the B16 melanoma cells died in response to IFNγ—highlighting the importance of using 3D cultures when exploring cancer cell biology in vitro." (PMID 33379189, 2020). "This in vitro two cell assay system measures interferon gamma (IFNγ) as a quantifiable readout which is released after the co-culture of antigen specific CD8+ T-cells with melanoma cells." (PMID 32231230, 2020). "Particularly, we found that IFNG, which was significantly overexpressed in melanoma tissues with high immune infiltration, was regulated by several of the hub lncRNAs." (PMID 32328190, 2020). "Treatment of murine experimental melanoma with CD40 immunotherapy resulted in upregulation of IFNγ signaling and subsequent expression of IDO by ECs." (PMID 33072086, 2020). "Following this period of exposure to putative antigens presented by melanoma cells, the T cells were restimulated with unmodified tumors and assayed for interferon-gamma (IFNγ) secretion, proliferation, and target cell killing." (PMID 32034147, 2020). "Exogenous TGFß diminished cell surface expression of HLA-ABC at baseline and, in some instances, was sufficient to diminish IFNγ induced HLA-ABC in melanoma cell lines." (PMID 32312968, 2020).
melanoma (continued). "Loss of ARID2 or BRD7 enhanced cytokine secretion in response to IFNγ and sensitized melanoma cells to T cell-mediated cytotoxicity in vitro." (PMID 33409155, 2020). "HVEM on melanoma cells inhibits the proliferation and production of IFNγ by B- and T-lymphocyte attenuator (BTLA)-positive tumor-specific CD8 T-cells." (PMID 33276788, 2020). "As a comparison, pre-treatment of melanoma cells with an HLA-ABC blocking antibody reduced IFNγ secretion by immune cells by over 95%." (PMID 32312968, 2020). "This high throughput screening assay quantitates IFNγ released upon recognition of the SB-3123p melanoma cells by Pmel-1 CD8+ T-cells." (PMID 32231230, 2020). "In melanoma metastasis to the lung, IFNγ, in combination with IL-17, models the TME in such a way that an effective immune response to the tumor can operate." (PMID 33138017, 2020). "SAHA and IFNγ pretreated melanoma cells were cocultured with activated human peripheral blood T cells." (PMID 33158915, 2020). "This in turn led to enhanced immune recognition of melanoma cells and an increase in IFNγ produced by the T cells." (PMID 32231230, 2020). "In conclusion, although the treatment with anti-PD-1 antibody reduces tumor growth in mice challenged with melanoma cells, we have found that this treatment induces the expression of PD-L1 and other immunosuppressive mediators via up-regulation of IFNγ." (PMID 30992475, 2019). "We engineered lipopolysaccharide (LPS) and interferon-γ (IFNγ)-matured, type-1-skewing DCs to express three melanoma tumor antigens (tyrosinase, MART-1 and MAGE-A6) through replication-defective adenovirus (AdV) transduction." (PMID 30761123, 2019). "Higher frequencies of T-cells expressing CD107a + IFNγ+ and central memory markers were observed in melanoma tumor-infiltrating lymphocytes (TIL), which persisted after drug removal and further expansion." (PMID 30728070, 2019). "Subsequent to this, the adaptive immune system plays a central role with effector CD4 + and CD8 + T-cells targeting melanoma cells through the actions of interferon-gamma (IFN-γ) or direct cytotoxic interactions." (PMID 31861163, 2019). "Expression of IL32 in human melanoma can be induced by TNFα or IFNγ and correlates with a treatment-resistant dedifferentiated genetic signature." (PMID 30953519, 2019). "Coupled to their enhanced effector functions—Ag-driven cytotoxity and IFNγ production—these engineered STAT5ca-CD8 T cells mediated efficient melanoma rejection as compared with conventional CD8 T effector cells." (PMID 31766350, 2019). "It is plausible, then, that IL32 is expanded within the microenvironment as a byproduct of the feedback loop between the anti-tumor inflammatory response (marked by TNFα and IFNγ) and dedifferentiation of melanoma." (PMID 30953519, 2019). "They further demonstrated that upregulation of perforin, granzymes, and IFNγ by STAT5 is the key to the enhancement of NK cell cytotoxicity against melanoma." (PMID 31569642, 2019). "piggyBac-mediated gene transfer of IFNγ into adipose-derived MSCs was used in a mouse model of melanoma to show that the IFNγ-expressing MSCs engrafted into tumor stroma, inhibited tumor growth and angiogenesis, and prolonged the survival of mice." (PMID 30899334, 2019). "It is possible that, at least in part, IFNγ exerts its cytotoxic effect by inhibiting FTO in melanoma cells." (PMID 31239444, 2019). "In melanoma, FTO impairs IFNγ-induced killing in melanoma cells in vitro via up-regulating PD-1, CXCR4, and SOX10 through suppressing YTHDF2-mediated-degradation and inhibits response to anti-PD-1 blockade immunotherapy." (PMID 31801551, 2019).